SPRY2 (sprouty RTK signaling antagonist 2)
Description:
Antagonist of fibroblast growth factor (FGF) pathways via inhibition of FGF-mediated phosphorylation of ERK1/2 (By similarity). Thereby acts as an antagonist of FGF-induced retinal lens fiber differentiation, may inhibit limb bud outgrowth and may negatively modulate respiratory organogenesis (By similarity). Inhibits TGFB-induced epithelial-to-mesenchymal transition in retinal lens epithelial cells (By similarity). Inhibits CBL/C-CBL-mediated EGFR ubiquitination.
Synonyms: hSPRY2; IGAN3
Tractability: Antibody: its Gene Ontology location is reachable by antibodies, with high confidence. PROTAC: ubiquitination databases record sites on it; its protein half-life has been measured.
Gene: Protein-coding gene on chromosome 13 (80,335,518 to 80,342,983, reverse strand). Ensembl gene ENSG00000136158.
Subcellular location: Cytoplasm, cytoskeleton; Cell projection, ruffle membrane
Subcellular location (Human Protein Atlas): Actin filaments; Microtubules
Pathways (Reactome):
Signal Transduction: EGFR downregulation; Spry regulation of FGF signaling
Gene Ontology:
Molecular function: protein binding; protein kinase binding; protein serine/threonine kinase activator activity; protein serine/threonine kinase inhibitor activity; protein kinase inhibitor activity; enzyme inhibitor activity; molecular function inhibitor activity
Biological process: cellular response to vascular endothelial growth factor stimulus; negative regulation of angiogenesis; negative regulation of apoptotic process; negative regulation of ERK1 and ERK2 cascade; negative regulation of protein ubiquitination; negative regulation of vascular endothelial growth factor signaling pathway; positive regulation of cell migration; positive regulation of ERK1 and ERK2 cascade; positive regulation of gene expression; positive regulation of peptidyl-serine phosphorylation; positive regulation of phosphatidylinositol 3-kinase/protein kinase B signal transduction; negative regulation of cell projection organization; negative regulation of epidermal growth factor receptor signaling pathway; negative regulation of epithelial to mesenchymal transition; negative regulation of fibroblast growth factor receptor signaling pathway; negative regulation of lens fiber cell differentiation; negative regulation of Ras protein signal transduction; negative regulation of transforming growth factor beta receptor signaling pathway; positive regulation of epidermal growth factor receptor signaling pathway; regulation of signal transduction
Cellular component: actin cytoskeleton; microtubule cytoskeleton; cytoskeleton; cytosol; membrane; nucleus; plasma membrane; ruffle membrane
Genetic constraint (gnomAD): Loss-of-function variants: 10 observed, 24.79 expected, observed/expected ratio (o/e) 0.4, 90% interval 0.25 to 0.68. The upper end of that interval is the gene's LOEUF score, 0.68, which puts it in group 2 of 6, group 1 being the genes least tolerant of losing a copy. Missense variants: 344 observed, 419.83 expected, observed/expected ratio (o/e) 0.82, 90% interval 0.75 to 0.9. Synonymous variants: 170 observed, 166.76 expected, observed/expected ratio (o/e) 1.02, 90% interval 0.9 to 1.16.
Homologues: Orthologues: macaque SPRY2 (100% identical), chimpanzee SPRY2 (97% identical), rabbit SPRY2 (97% identical), guinea pig SPRY2 (97% identical), pig SPRY2 (97% identical), mouse Spry2 (97% identical), rat Spry2 (95% identical), tropical clawed frog spry2 (74% identical), zebrafish spry2 (53% identical), Drosophila melanogaster sty (35% identical). Paralogues in human: SPRY1 (52% identical), SPRY4 (40% identical), SPRY3 (38% identical).
Diseases named in the same sentence as SPRY2 in open-access papers:
SPRY2 is named in the same sentence as 122 diseases in open-access papers, as found by Europe PMC text mining. Sharing a sentence is not in itself a finding about the gene and the disease. The quoted sentences say what the papers report.
breast carcinoma (26 papers, 2011 to 2025). "SPRY2 has been associated with cancer progression in particular in breast cancers and melanomas." (PMID 39494610, 2024). "SPRY2 expression is downregulated in various cancers, including prostate, liver, lung, and breast cancers." (PMID 39778021, 2025). "For example, Spry1 and Spry2 levels are decreased in prostate and breast cancer, whereas downregulation of Spry2 has been described in hepatocellular carcinoma, B-cell lymphoma, or endometrial carcinoma, among others." (PMID 38670941, 2024). "Consistent with our findings in vitro, SPRY2 knockdown in fibroblasts significantly increased the tumor burden of breast cancer in subcutaneous xenograft model." (PMID 37507768, 2023). "SPRY2 knockdown in fibroblasts promoted tumor growth and distant metastasis of breast cancer in mice." (PMID 37507768, 2023). "Decreased SPRY2 expression in stroma of breast cancer predicts a poor prognosis and contributes to tumor progression." (PMID 37507768, 2023). "In this study, we identified the downregulation of Sprouty family gene SPRY2 in CAFs of breast cancer." (PMID 37507768, 2023). "As a result, SPRY2 expression was highly expressed in stroma of normal breast, but the expression was decreased in the stroma of breast cancer." (PMID 37507768, 2023). "The downregulation of SPRY2 has been shown in chronic lymphocytic leukemia, non-small cell lung cancer, hepatocellular carcinoma, breast cancer, and prostate cancers, highlighting its tumor suppressor function." (PMID 37047796, 2023). "SPRY2 functions as a tumor suppressor in most cancers and its expression has been found to be low in a variety of cancers, such as prostate cancer, breast cancer, lung cancer, liver cancer and colon cancer." (PMID 36749775, 2023). "We found low SPRY2 expression in CAFs predicted more lymphnode metastasis, bigger tumor size and higher frequency of survival event in patients with breast cancer." (PMID 37507768, 2023). "Here, we identified another gene SPRY2, whose decreased expression promotes CAFs phenotypes in breast cancer." (PMID 37507768, 2023). "Here, by comparing the gene expression patterns in CAFs and normal fibroblasts, we found SPRY2 expression was significantly decreased in CAFs and decreased SPRY2 expression was correlated with worse prognosis in breast cancer patients." (PMID 37507768, 2023). "To elucidate the biological functions of SPRY2 in stroma, we first compared the gene expression profiles between SPRY2-low group and SPRY2-high group using the RNA-seq data of CAFs from breast cancers patients in GSE10797 and GSE9014." (PMID 37507768, 2023). "Multivariate Cox regression analysis found low SPRY2 expression was one of the independent clinicopathological factors for poor overall survival in breast cancer patients." (PMID 37507768, 2023). "We then performed Reactome analysis of Spry2-low group and Spry2-high group by using single-cell-sequencing data of fibroblasts isolated from mammary tumors of MMTV-PyMT mice (GSE111229)." (PMID 37507768, 2023). "For breast cancer, we present an interaction between SPRY2 and C0L10A1 and for kidney one between TFAP2A and SGPP1." (PMID 32859146, 2020). "Sprouty (Spry) family genes Spry1, Spry2 and Spry4 are differentially expressed in breast cancer, but Spry3 is rarely expressed." (PMID 31671542, 2019). "Essentially, these studies have shown that in certain disease states such as carcinomas of the breast, liver, lung and prostate, the levels of Spry proteins, especially Spry2, are decreased and probably contribute toward the pathogenesis of the disease." (PMID 28196140, 2017). "SPRY2, an inhibitor of RAS/mitogen signaling, has been previously associated with prognosis of breast cancer." (PMID 27078887, 2016).
breast carcinoma (continued). "Similar data were reported for the behavior of multiple myeloma cells that possessed a knock-down in expression of the SPRY2 gene and after pharmacological inhibition of expression of the urokinase-type plasminogen activator in human breast carcinoma cells." (PMID 26959111, 2016). "Several studies have demonstrated that the expression of SPRY2 was downregulated or inhibited in prostate cancer, breast cancer and malignant glioma, leading to the deregulation and overactivation of MAPK/ERK signaling in tumor cells." (PMID 25633921, 2015). "Together, these data show that Spry2 expression is lost during cancer progression and suggest that Spry2 protects normal epithelium from breast cancer in the mouse mammary gland." (PMID 24718286, 2014). "miR-24 is transcriptionally upregulated in breast cancer with lymph node metastasis in part by MYC, and overexpression of miR-24 in MCF-7 breast cancer cells promotes invasion and metastasis through repression of SPRY2 and subsequent MAPK activation." (PMID 25364765, 2014). "They finally indicated that the MCF-7 breast cancer cells transfected with a dominant-negative mutant of Spry2 proliferated faster and exhibited anchorage-independent growth in vitro and formed larger tumors in vivo." (PMID 24744103, 2014). "As an initial step in understanding Spry2 function in breast cancer biology, we examined Spry2 expression during tumor progression in the MMTV-PyMT mouse model of luminal B breast cancer." (PMID 24718286, 2014). "Spry2 expression is greatly reduced in human breast cancer, suggesting that it plays a role in protecting mammary epithelium against tumorigenesis." (PMID 24718286, 2014). "Sprouty family genes were differentially expressed across the five intrinsic breast cancer subtypes, with high expression of Spry 1 and Spry2 in normal-like cancers and higher expression of Spry4 in basal-like and normal-like cancers." (PMID 21909357, 2011). "This supports the role of Spry2 as a tumour suppressor gene in breast cancer, and its role in therapeutic resistance to trastuzumab." (PMID 21909357, 2011). "Also consistent with its tumour suppressor function, Spry2 expression decreases with increasing histological grade, and shows a strong association with relapse-free survival in a meta-analysis of over one thousand primary breast carcinomas, including in multivariate analysis." (PMID 21909357, 2011). "Quantitative protein expression levels of Spry2 stratified patients for outcome in a series of 122 trastuzumab-treated breast cancers." (PMID 21909357, 2011). "The only published report of expression of Sprouty in breast cancer showed decreased expression at transcript level of Spry1 and Spry2 in 78% and 96% respectively of a small panel of breast cancers (n = 50)." (PMID 21909357, 2011). "In breast cancer, Spry2 has been shown to be down-regulated at gene expression level compared to normal breast epithelium, which we confirmed in a meta-analysis of published gene expression data." (PMID 21909357, 2011). "Additionally, the c-MYC-regulated miR-23a ~ 27a ~ 24-2 cluster promotes cell invasion and hepatic metastasis of breast cancer by targeting SPRY2." (PMID 39112518, 2024). "Moreover, we noticed that knockdown of SPRY2 also enhanced in vivo lung metastasis of breast cancer cells." (PMID 37507768, 2023). "To investigate whether stromal SPRY2 affected breast cancer CSC properties and also clarify whether the effects were dependent on stroma glycolysis, we performed sphere-formation assays." (PMID 37507768, 2023). "As shown by our work, targeting tyrosine phosphorylation of LDHA by SPRY2 might be prospective in stroma of breast cancer." (PMID 37507768, 2023). "Down-regulation of SPRY1 and SPRY2 occurs in prostate, liver, lung, and breast cancers." (PMID 37507768, 2023). "Here, we further sought to delineate the role and mechanisms of SPRY2 in CAFs of breast cancer." (PMID 37507768, 2023).
breast carcinoma (continued). "In this study, we identified SPRY2 as a novel regulator of CAFs in breast cancer development." (PMID 37507768, 2023). "Other negatively correlated validated targets for miR‐21‐5p included the mRNAs of LIFR, a metastasis suppressor in breast cancer, and SPRY2, a negative regulator of RAS and MAPK signalling, with Pearson correlations of −0.46 and −0.42, respectively (P = 4.9e − 60 and 5.4e − 48)." (PMID 35182081, 2022). "Thus, the decreased expression of miR-181a in NK cells in breast cancer patients would help to fine-tune NK cell-mediated immune response to breast cancer by targeting Spry2." (PMID 28145491, 2017). "Indeed, in hepatocellular carcinoma and breast cancer, a decrease in Spry2 levels has been correlated with poor prognosis and a decrease in patient survival." (PMID 28196140, 2017). "Several studies showed that SPRY2 gene expression was downregulated and inhibited in prostate cancer, breast cancer, malignant glioma and other tumor types, leading to uncontrolled and overactivated mitogen-activated protein kinase/extracellular-regulated kinase (MAPK/ERK) signaling in tumor cells." (PMID 25825239, 2015). "Importantly, Spry2 gene is greatly down-regulated in subgroups of breast cancer, suggesting that it protects mammary epithelium from tumorigenesis." (PMID 24718286, 2014). "Spry2 was found as an independent prognostic factor that may identify breast cancer patients with a more favorable outcome even when tumors exhibit poor pathological features." (PMID 24744103, 2014). "Furthermore, SPRY2 has been shown to be downregulated in a number of cancers, including breast cancer." (PMID 23573284, 2013). "Since decreased expression of tumor SPRY2 has been considered to be a significant independent prognostic factor and plays a cancer-promoting role in breast cancer, targeting SPRY2 might be a promising approach to achieve therapeutic effects in combating breast cancer." (PMID 37507768, 2023). "Moreover, Spry2 expression is reduced the MMTV-PyMT mouse model of breast cancer." (PMID 24718286, 2014). "To further determine the protein expression of SPRY2 in fibroblasts of breast cancer, we performed immunohistochemical (IHC) analysis in a human breast cancer tissue microarray (TAM) from 132 cases of breast cancer patients." (PMID 37507768, 2023). "This occurs through the targeting of Sprouty2 (SPRY2) and subsequent activation of the p44/42 MAPK signaling pathway in breast cancer." (PMID 37445965, 2023). "Differently from the molecular mechanism of SPRY2 on glycolysis in liver cancer, SPRY2 inhibits glycolysis in a MAPK-independent manner in breast cancer CAFs." (PMID 37507768, 2023). "For instance, in prostate and breast cancers SPRY1 and SPRY2 levels are inhibited, whereas in hepatocellular carcinoma only SPRY2 but not SPRY1 expression is decreased." (PMID 26392417, 2015). "Changes in expression of Spry2 and feedback inhibition on trastuzumab resistance were studied in SKBr3 and BT474 breast carcinoma cell lines using cell viability assays." (PMID 21909357, 2011). "SPRY2 has been reported to interact with SRC and SRC could phosphorylate LDHA at tyrosine 10 in breast cancer." (PMID 37507768, 2023). "Collectively, this work identified SPRY2 as a negative regulator of CAF activation, and SPRY2 in CAFs may potentially be therapeutically targeted in breast cancer treatment." (PMID 37507768, 2023). "In terms of epigenetic modifications, the promoters of Spry4 and Spry2 have been shown to be hypermethylated in prostate cancer, but not breast cancer." (PMID 28196140, 2017). "Together, these data demonstrate that Spry2 is a negative feedback regulator of FGF signaling, a major RTK pathway essential for mammary gland development and breast cancer biology." (PMID 24718286, 2014).
prostate carcinoma (17 papers, 2011 to 2025). A carcinoma that arises from epithelial cells of the prostate gland. "Importance of molecular events such as SPRY2 loss or HER2 activation in tumoral IL6 production in clinical prostate cancers needs further investigation." (PMID 29540470, 2018). "Using murine pre‐clinical models of prostate cancer, we show how SPRY2 deficiency leads to treatment resistance." (PMID 29540470, 2018). "We show that SPRY2 loss leads to an androgen self‐sufficient form of CRPC representing an ARPC (AR‐active prostate cancer) type of clinical CRPC." (PMID 29540470, 2018). "We have previously shown how SPRY2 deficiency cooperates with loss of PTEN or PP2A tumour suppressor activity to drive prostate cancer initiation." (PMID 29540470, 2018). "We next investigated the effects of SPRY2 on growth under hormone deprivation in LNCaP cells, an AR‐proficient prostate cancer cell line deficient for both SPRY2 and PTEN (Fig EV1K)." (PMID 29540470, 2018). "In contrast, reduction of SPRY2 (sprouty homolog 2) expression causes hyperactivation of PI3K/AKT signaling to drive prostate cancer cell proliferation and invasion by enhanced internalization of EGFR and sustained signaling at early endosomes in a PTEN-dependent manner." (PMID 33641663, 2021). "Here, using both in vitro and in vivo model systems including human prostate orthograft and genetically modified pre‐clinical murine models, we uncovered a functional role of SPRY2 deficiency in the progression of prostate cancer to CRPC state through bidirectional tumour–host interactions." (PMID 29540470, 2018). "Inactivation of tumour suppressors such as PTEN and Sprouty2 (SPRY2) drives aggressive treatment resistant prostate cancer." (PMID 33033111, 2020). "The genetically engineered mouse model with Probasin-mediated deletion of Pten and Spry2 (namely PbCre Ptenfl/flSpry2fl/+, referred to as the SP model hereafter) models clinical invasive prostate cancer." (PMID 33033111, 2020). "Previous studies have demonstrated that decreased SPRY2 expression contributes to the tumorigenesis and progression of liver cancer, prostate cancer, and endometrial carcinoma." (PMID 30837325, 2019). "Prostate cancer patients with low SPRY2 levels, defined as below median histoscore, showed significantly lower relapse‐free and overall survival following ADT." (PMID 29540470, 2018). "To evaluate the clinical significance of SPRY2 deficiency in governing treatment response, we investigated the prognosis of ADT‐treated prostate cancer patients based on the tumour levels of SPRY2." (PMID 29540470, 2018). "We next tested the sensitivity of SPRY2‐deficient cells to the CYP17A1 inhibitor abiraterone, which improves the treatment response of prostate cancer patients when combined with standard‐of‐care ADT." (PMID 29540470, 2018). "Surprisingly, we have demonstrated that single germline deletions of either Spry1 or Spry2 result in the development of prostatic intraepithelial neoplasias, the generally accepted precursor of prostate cancer." (PMID 26075267, 2015). "Our description of reduced SPRY2 expression is consistent with other studies of clinical samples of prostate cancer." (PMID 26075267, 2015). "Using an integrated approach to study treatment resistance in clinical and murine pre‐clinical models of prostate cancer, we show that loss of tumour suppressor SPRY2, a negative regulator of receptor tyrosine kinase signalling, leads to CRPC." (PMID 29540470, 2018). "Similarly, patients with low SPRY2 expression in TCGA prostate cancer dataset also have significantly reduced relapse‐free survival (Fig EV1A; Cancer Genome Atlas Research, 2015)." (PMID 29540470, 2018). "To explore if SPRY2 could mediate resistance to ADT independent of PTEN status, we investigated the levels of AR, PTEN and SPRY2 in a panel of prostate cancer cell lines (Fig EV1K)." (PMID 29540470, 2018). "There are limited reports of SPRY1 and SPRY2 suppression in clinical samples of prostate cancer." (PMID 26075267, 2015).